ARID1A (AT-rich interaction domain 1A)
Diseases named in the same sentence as ARID1A in open-access papers (continued):
Sharing a sentence is not in itself a finding about the gene and the disease.
tumor (continued). "The low immune activity along with activation of genes that are associated with HCC development in low-ARID1A subtype indicate that ARID1A may have tumor suppressive activity and suggests the possibility of ARID1A as a prognostic biomarker in HCC patients." (PMID 32878261, 2020). "Thus, in addition to its function as a chromatin remodeler, ARID1A is regarded as a tumour suppressor gene." (PMID 31906887, 2020). "We identified 13 variants that existed in cfDNA, but not in tumor DNA from comparison analysis, and three of these were located in driver genes (ARID1A, NFE2L2 and PIK3CA)." (PMID 31641155, 2019). "In addition, ARID1A is one of the most frequently deleted genes in a variety of tumor types, and knockdown of ARID1A leads to a failure of cell cycle arrest." (PMID 31480737, 2019). "Specifically, the authors showed that while ARID1A supports initial HCC development, ARID1A loss after tumor establishment further accelerates and increases metastatic potential of HCC, suggesting the importance of protein subunit dosage in the proper regulation of global transcription." (PMID 31056726, 2019). "In spite of a high frequency of ARID1B and ARID1A mutations in this series, only one tumour showed absence of expression of ARID1A." (PMID 30641862, 2019). "While these models confirmed its tumor suppressive role in various cancers, some striking observations were made which indicated that ARID1A could also play a pro-tumorigenic role in certain contexts." (PMID 31217031, 2019). "Low expression levels of ARID1A gene may contribute to the tumor's tendency to transform malignantly." (PMID 31241714, 2019). "Surprisingly, in contrast to its described tumor suppressive role, we observed that the deletion of ARID1A led to a severe impairment in proliferation in two cell lines (HCT116 and DLD1) while proliferation in the other two cell lines (COLO320DM and HT29) was unaffected." (PMID 31217031, 2019). "Interestingly such a situation creates the best scenario for a synthetic lethal interaction between the loss of ARID1A expression and inhibition of the PI3K/AKT pathway in tumor cells." (PMID 31731647, 2019). "However, recent studies demonstrated that ARID1A has dual roles in both oncogenicity and tumor suppression." (PMID 30849962, 2019). "ARID1A can promote tumor initiation through CYP450-mediated oxidative damage." (PMID 30849962, 2019). "Then, the results that ARID1A and BRCA2 were more frequently mutated in diffuse-type C-II GCs than in C-I GCs suggest that many mutations may be induced in the tumor by the loss of function of these tumor suppressors." (PMID 30866995, 2019). "Furthermore, the tyrosine kinase inhibitor dasatinib mediates apoptosis by targeting YES1 inhibition in ARID1A-null tumor cells." (PMID 31238554, 2019). "It suggests that other factors beyond MSI, such as the reduced tumor aneuploidy level and deregulation of ARID1A-mediated pathways, may also contribute to the increased tumor immunity in ARID1A-mutated GI cancers." (PMID 31277418, 2019). "Depletion of ARID1B may result in an overbalance of the tumor suppressing properties of ARID1A within the SWI/SNF complexes, resulting in decreased proliferation of un-irradiated cells with wild-type ARID1A." (PMID 31796878, 2019).
tumor (continued). "Thus, even though ARID1A is mainly described as a tumor suppressor, recent investigations point to the importance of targeting ARID1A in order to sensitize cancer cells to chemotherapy and radiation." (PMID 31847141, 2019). "Interestingly, a different sample with a nonsense mutation p.(R1721X) with VAF 19% showed immunohistochemical expression of ARID1A in <1% of tumor nuclei." (PMID 31745173, 2019). "We identify a previously unknown context-dependent tumor-supporting function of ARID1A in CRC downstream of KRAS signaling." (PMID 31217031, 2019). "In addition, the fact that HuR–ARID1A interaction contributes to radiation resistance points that ARID1A can play roles as a tumor promoter even though it is mainly described as a tumor suppressor." (PMID 31847141, 2019). "ARID1A immunoreactivity was detected in tumor cell nuclei, as we previously reported." (PMID 29890703, 2018). "Multivariate Cox regression analysis with tumor related death as endpoint for ARID1A." (PMID 29451900, 2018). "Loss or significant reduction of ARID1A protein expression is associated with heterozygous ARID1A mutations 1, 8, 9, suggesting a dominant‐negative tumour suppressor role (see 10 for a comprehensive review)." (PMID 29659191, 2018). "ARID1A is a tumor suppressor encoding a subunit for switch-sucrose nonfermentable (Swi-SNF) box, and is crucial for chromatin remodeling." (PMID 30008616, 2018). "The patient did not have an identifiable ARID1A mutation and their tumour had an ARID1A IHC score of 12 (>80% of tumour staining strongly)." (PMID 29659191, 2018). "Although speculative, we hypothesize that tumor-derived ARID1A mutant OCCC lines may have acquired additional genetic alterations causing a more stable phenotype compared to cell lines generated by CRISPR/Cas9 mediated ARID1A manipulation." (PMID 29760405, 2018). "It is important to note that ARID1A mutations and HNF-1beta overexpression act at different stages of tumor development, genetic inactivation of ARID1A activating the carcinogenetic process, while epigenetic activation of HNF-1beta being involved in tumor phenotype and cancer progression." (PMID 29389895, 2018). "A somatic frameshift indel in ARID1A was also found in the MSI tumor sample." (PMID 28683819, 2017). "Expression of PTEN, beta-Catenin, and ARID1A was observed in all tumour samples." (PMID 28103826, 2017). "We assessed whether ATR activity was impaired in HCT116 ARID1A−/− tumour cells as well as in a panel of human tumour cell lines characterized according to their ARID1A status." (PMID 27958275, 2016). "To investigate this possibility, we next tested whether co-losses of PBRM1 and ARID1A affect tumor growth in a xenograft model when compared to single losses." (PMID 27764136, 2016). "In addition, ARID1A expression was also statistically different between tumor and adjacent mucosa tissues (p-value = 0.009) and between tumor and peritumoral infiltrate samples (p-value = 0.018)." (PMID 27566570, 2016). "The results suggest that ARID1A loss has a greater tumor-promoting effect than PBRM1 loss, indicating that xenograft analysis is a useful tool to investigate how these losses impact on tumor behavior, either alone or in combination." (PMID 27764136, 2016).
tumor (continued). "It is thought that ARID1A contributes to tumor suppression in three main aspects." (PMID 27354232, 2016). "To verify the role of ARID1A in vivo, we performed a xenograft tumor assay in mice." (PMID 27323812, 2016). "ARID1A loss contributes to tumor growth significantly, but it is unlikely to be the major mechanism of tumor suppression by PBRM1." (PMID 27764136, 2016). "Although it has been demonstrated that ARID1A has important tumor suppressive functions in cancer, whether ARID1A regulates ROS has not been reported." (PMID 27486766, 2016). "Moreover, functional studies present the evidence that ARID1A participates in several canonical tumor suppression processes, such as proliferation and apoptosis." (PMID 27354232, 2016). "Our subgroup analyses revealed that the prognostic role of ARID1A deficiency in GC was independent of tumor stage (T and N), differentiation grade and MSI status." (PMID 27354232, 2016). "The correlation between ARID1A expression loss and poor OS remained in subgroup analyses, regardless of tumor clinical stage, deficiency rate of ARID1A expression, sample size, tumor differentiation and MSI status." (PMID 27354232, 2016). "Finally, in order to learn the impact of combined losses, we compared the tumor growth after cells acquired losses of ARID1A, PBRM1, or both in a xenograft model." (PMID 27764136, 2016). "Loss of ARID1A function is associated with dysregulation of the PI3K/Akt signaling pathway, which may have a synergistic effect on tumor development." (PMID 26384299, 2015). "ARID1A was previously shown to be a tumor suppressor in gastrological cancers." (PMID 25887147, 2015). "ARID1A is a member consisting of SWI/SNF chromatin remodeling complexes from which disordered chromatin regulation can induce a distinct mechanism contributing to tumor development." (PMID 26524630, 2015). "Similarly, the present study found that ARID1A protein expression was decreased in patient-derived HCC tumor tissues, and that decreased expression was significantly correlated with lymph node and distant metastasis, and poor prognosis." (PMID 25975202, 2015). "Although a non-synonymous mutation (chr1 27056157; NP_006006, p.D385N) in ARID1A (mutated in 10–16% of HCCs) was identified, the tumor-mutated allele was not transcribed." (PMID 26631547, 2015). "Likewise, ARID1A is a wide-spread tumor suppressor frequently inactivated in various epithelial cancers." (PMID 26312500, 2015). "ARID1A belongs to the Brahma-related gene 1 (BRG1)-associated factor, which is a core subunit of the SWI/SNF complexes, and was recently found to be mutated in several tumor types, including ovarian, bladder and gastric cancers." (PMID 24955791, 2014). "The observation that the ARID1A-negative group is similar to the genomically unstable tumor subgroup of Sjödahl suggests that ARID1A might contribute to the maintenance of genomic stability, possibly through its role in chromatin remodeling." (PMID 23650517, 2013). "Characteristics of the patients from whom fresh tumor was used for ARID1A sequence analysis." (PMID 23650517, 2013). "Secondly, it confirms that there is a close cooperative mechanism between ARID1A mutations and PI3K/AKT pathway alterations that might be of importance for early tumor detection, as well as in a therapeutic context." (PMID 24036443, 2013). "Further work is required to assess the mechanisms through which ARID1A inactivation favors tumor progression, to determine how it modulates the effects of oncogenes or tumor suppressors, and whether different mutations have distinct biological effects." (PMID 23650517, 2013). "ARID1A (AT-rich interactive domain 1A) has recently been identified as a tumor suppressor gene." (PMID 23349767, 2013). "In contrast to tumor-adjacent atypical endometriosis, no mutations or loss of ARID1A expression were found in the distal non-atypical endometriotic tissue of the same patients." (PMID 24036443, 2013).
tumor (continued). "It is through this complex that ARID1A probably exerts its role as a tumor suppressor." (PMID 24036443, 2013). "Furthermore, using in vitro cell model, we also investigated the tumor suppressor role of ARID1A in gastric cells in detail." (PMID 22808142, 2012). "Though the interpretation of mutations in mismatch repair-deficient tumors is challenging [Kern, 2002], the fact that approximately 40% of the CRCs with ARID1A mutations did not have MSI leaves little doubt that ARID1A plays a role in this tumor type." (PMID 22009941, 2012). "ARID1A has been showed to function as a tumor suppressor in various cancer types." (PMID 22808142, 2012). "It is likely that loss of ARID1A protein expression is not as important for tumor progression or response to treatment as it is for tumor initiation." (PMID 21614196, 2010). "Loss of ARID1A leads to the accumulation of R‐loops, which generates cytoplasmic DNA that activates the STING‐I type interferon signalling pathway, inducing gene expression that promote anti‐tumour immunity, providing a theoretical basis for improving immune checkpoint blockade (ICB) therapy." (PMID 39779467, 2025). "Furthermore, ARID1A knockdown stimulates neovascularization through transcriptional modulation of Ang-2; conversely, anti-vascular therapy attenuates the invasive phenotypes of tumor." (PMID 40463905, 2025). "Similarly, the role of ARID1A in PC remains unclear with both tumour promoting and suppressing effects reported." (PMID 39885328, 2025). "The role of AT-rich interaction domain 1A (ARID1A), a component of the SWI/SNF chromatin remodeling complex, is also crucial; its loss, triggered by inflammation-induced IKKβ activation, leads to increased MDSC chemotaxis and enhances tumor progression through the IKKβ/ARID1A/NF-κB feedback loop." (PMID 40556678, 2025). "Here, we compared the effects of ARID1A depletion and re‐expression in normal‐like and tumor‐like urothelial bladder cell models to gain further insight regarding the consequences of ARID1A inactivation and to identify pathways that might serve as possible targets for treatment." (PMID 40170512, 2025). "Notably, an in vivo study employing animal models demonstrated that combining HDAC6 inhibition via ACY1215 with ICIs constitutes a potential therapeutic approach for ARID1A-mutated OCCC, effectively limiting tumor progression through a cytotoxic T-cell-dependent mechanism." (PMID 41383608, 2025). "However, unlike revertible tumor suppressors such as BRCA1/2, some ATRi synthetic lethal partners (e.g., ARID1A) may be essential for tumor fitness, potentially limiting reversion-based resistance." (PMID 40869030, 2025). "Hence, ARID1A-mutated tumours may depend on ARID1B for proliferation, suggesting a synthetic lethality combination between ARID1A and ARID1B and thus providing an opportunity for personalised targeting of cancer growth." (PMID 41278204, 2025). "ARID1A overexpression and increased oxidative stress align with established studies indicates that antioxidants can suppress tumor initiation but might, in contradiction, promote tumor progression when redox balance is disrupted." (PMID 41514650, 2025). "However, recent evidence suggests that epigenetic silencing via promoter hypermethylation may similarly disrupt the tumor-suppressive function of ARID1A." (PMID 41215803, 2025).
tumor (continued). "Using immunostaining, we could detect Arid1a upregulation at the protein level in tumours, suggesting that non-mutational stabilisation of Arid1a could be required in cancer cells." (PMID 40386410, 2025). "Additionally, several mutations not previously reported in OSCC sequencing studies were detected in 7% of cases including mutations in ARID1A (chromatin remodeling), BIRC6 (apoptosis inhibition), DCC (neural regulation and tumor suppression), and NCOR1 (transcriptional inhibition)." (PMID 41154345, 2025). "LoF ARID1A mutations independent of other mutations are not sufficient for tumorigenesis but may accelerate tumor development driven by co-occurring oncogenes." (PMID 38275886, 2024). "Furthermore, all patients with an ARID1A mutation (6%) had microvascular invasion and significantly larger tumours than the patients without ARID1A mutation." (PMID 38536546, 2024). "Targeting EZH2 with specific inhibitors is particularly relevant in ARID1A-mutated cancers since EZH2 is known to influence tumor-infiltrating lymphocytes, thereby contributing to creating an immunosuppressive tumor microenvironment that facilitates immune evasion by tumor cells." (PMID 38893181, 2024). "Multiple studies suggest that ARID1A may act as a tumor suppressor." (PMID 38384812, 2024). "Nevertheless, a recent study proposed that any ARID1A loss—irrespective of the percentage area of the tumor affected (heterogeneous/clonal/diffuse)—may be associated with specific clinicopathological or molecular features." (PMID 38893181, 2024). "Through both univariable and multivariable analyses, we also revealed that high CDKN2A and SMAD4 mutation abundances in ctDNA but not in tumor and high ARID1A mutation abundances in both ctDNA and tumor at baseline and/or the second measurement were linked to inferior OS and/or PFS." (PMID 38378604, 2024). "Notably, all other ARID1A mutants showed high protein expression, and the responding patient also had a high tumor mutational burden (TMB); there was no clear difference in TMB between patients with or without clinical benefit." (PMID 37934611, 2024). "In addition, HDAC6 inhibition largely inhibited tumor growth in ARID1A-mutant tumors." (PMID 37109525, 2023). "According to this study, synchronous ARID1A loss and PIK3CA overactivation synergistically induced upregulation of IL-6, a cytokine that triggers and is triggered by the JAK/STAT pathway, thereby initiating a signaling cycle that promotes tumor cell growth and differentiation." (PMID 37627318, 2023). "Interestingly, any loss of ARID1A expression, regardless of the percentage area of the tumor, was shown to be relevant." (PMID 36916408, 2023). "For example, we show that GAs in genes such as ARID1A, SMARCA4 and ATR are associated with TMB-high status in a tumour type-specific manner and may thus represent additional biomarkers for immunotherapy in these tumour types." (PMID 37821580, 2023). "ARID1A loss is associated with enhanced activation of the PI3K/AKT pathway in vitro, as well as activation of mTOR signalling and increased expression of SOX9, a gastrointestinal stem cell marker, in tissue microarrays, cell lines, patient xenograft tumours, and mouse models." (PMID 38275587, 2023). "Additionally, it has been shown that ARID1A deficiency may lead to a synthetic lethal therapy response to Ataxia telangiectasia and Rad3 related (ATR) inhibitors in several tumor entities." (PMID 36269546, 2022). "Notably, recent studies revealed the vital effect of ARID1A on tumor immunity." (PMID 35198440, 2022). "A study performing whole‐exome sequencing of 98 tumour biopsies from primary tumours and their paired abdominopelvic metastases demonstrated that ARID1A was frequently mutated in the branches of EC phylogenesis, suggesting that ARID1A is involved in EC tumour progression rather than its initiation." (PMID 35167193, 2022).